CPSF1 (cleavage and polyadenylation specific factor 1)
Description:
Component of the cleavage and polyadenylation specificity factor (CPSF) complex that plays a key role in pre-mRNA 3'-end formation, recognizing the AAUAAA signal sequence and interacting with poly(A) polymerase and other factors to bring about cleavage and poly(A) addition. This subunit is involved in the RNA recognition step of the polyadenylation reaction. May play a role in eye morphogenesis and the development of retinal ganglion cell projections to the midbrain (By similarity).
Synonyms: CPSF160; HSU37012; MYP27; P/cl.18
Tractability: PROTAC: ubiquitination databases record sites on it; its protein half-life has been measured.
Gene: Protein-coding gene on chromosome 8 (144,393,229 to 144,409,861, reverse strand). Ensembl gene ENSG00000071894.
Subcellular location: Nucleus, nucleoplasm
Subcellular location (Human Protein Atlas): Nucleoplasm
Pathways (Reactome):
Metabolism of RNA: Processing of Intronless Pre-mRNAs; Transport of Mature mRNA Derived from an Intronless Transcript; mRNA 3'-end processing; mRNA Polyadenylation; tRNA processing in the nucleus
Disease: Dengue Virus-Host Interactions
Gene expression (Transcription): RNA Polymerase II Transcription Termination
Gene Ontology:
Molecular function: enzyme binding; mRNA 3'-UTR AU-rich region binding; protein binding; nucleic acid binding
Biological process: mRNA 3'-end processing; co-transcriptional RNA 3'-end processing, cleavage and polyadenylation pathway
Cellular component: mRNA cleavage and polyadenylation specificity factor complex; nucleoplasm; nucleus
Genetic constraint (gnomAD): Loss-of-function variants: 105 observed, 166.8 expected, observed/expected ratio (o/e) 0.63, 90% interval 0.54 to 0.74. The synonymous counts are far from expectation, so gnomAD's model fits this gene poorly and the ratio says little. Missense variants: 1,731 observed, 1,979.5 expected, observed/expected ratio (o/e) 0.87, 90% interval 0.84 to 0.91. Synonymous variants: 1,024 observed, 846.09 expected, observed/expected ratio (o/e) 1.21, 90% interval 1.15 to 1.27.
Homologues: Orthologues: chimpanzee CPSF1 (99% identical), dog CPSF1 (97% identical), mouse Cpsf1 (97% identical), rat Cpsf1 (96% identical), guinea pig CPSF1 (95% identical), tropical clawed frog cpsf1 (81% identical), zebrafish cpsf1 (80% identical), Drosophila melanogaster Cpsf160 (47% identical), Caenorhabditis elegans cpsf-1 (34% identical). Paralogues in human: DDB1 (18% identical), SF3B3 (17% identical).